CRP (C-reactive protein)
Diseases named in the same sentence as CRP in open-access papers (continued):
Sharing a sentence is not in itself a finding about the gene and the disease.
Hypoalbuminemia (continued). "The main determinants of the unbalanced bone turnover were hypoalbuminemia for the CTX/Ocn ratio (OR 19.8, p < 0.01) and high CRP for the CTX/PINP ratio (OR 5.3, p < 0.01) in the multivariate regression analysis." (PMID 34182958, 2021). "However, the joint effect of hs-CRP and hypoalbuminemia among CAD patients remains unclear." (PMID 34961476, 2021). "Although preoperative albumin levels are predictive of postoperative complications, postoperative hypoalbuminemia occurs normally following TKA and follows a predictable postoperative course that mirrors the course of CRP." (PMID 33592030, 2021). "Inflammation markers were elevated (C-reactive protein, CRP, 132 mg/L, erythrocyte sedimentation rate, ESR, 89 mm/h) and slight hypoalbuminemia was found (3.4 g/dL)." (PMID 33676575, 2021). "Some biomarkers are related to moderate and severe COVID-19 infection like low lymphocytes absolute numbers or increased levels of serum C-reactive protein (CRP), hypoalbuminemia, alanine aminotransferase, lactate dehydrogenase, ferritin, and/or D-dimer." (PMID 34066892, 2021). "Laboratory investigations also showed elevated C-reactive protein (CRP) 8.5 mg/dl (normal reference ≤0.5 mg/dl), hypoalbuminemia (3 g/dl) and elevated transaminase levels: alanine aminotransferase (ALT) of 132 U/L, alkaline phosphatase (ALP) of 375 U/L." (PMID 32787862, 2020). "Hotelling's t analysis revealed significant differences among the presurgical albumin infusion (B), presurgical normal protein diet (C), and hypoalbuminemia (D and E) diet groups in terms of serum levels of albumin, TNF-α, IL-1, IL-6, CRP, and MMP-8 (P=0.01)." (PMID 32518615, 2020). "The hypoalbuminemia seen in the 2% casein diet group can be attributed to significant increases in the levels of the acute-phase proteins TNF-α, IL-1, IL-6, and CRP compared with the controls." (PMID 32518615, 2020). "The survival was significantly influenced by only CRP (P <0.001), lymphocyte counts (P =0.013), hypoalbuminemia (P =0.002), PNI (P <0.001) and CRP/PNI ratio (P <0.001), while all variables were compared separately to survival status." (PMID 28977869, 2017). "The persistence of elevated CRP, AST, ALT levels, a persistent hyponatremia and hypoalbuminemia after IVIG therapy, also had a statistical significant correlation with IVIG doses." (PMID 27806720, 2016). "Non responders showed higher levels of D-dimer and gamma-GT pre-IVIG, persistent high levels of D-dimer, CRP, AST, ALT, hypoalbuminemia and hyponatremia after IVIG." (PMID 27806720, 2016). "Relationships between preoperative CRP and hypoalbuminemia on POD 3, between preoperative CRP and hypoalbuminemia on POD 7 and between CRP on POD 3 and hypoalbuminemia on POD 7 were examined by receiver operating characteristic analysis." (PMID 26530188, 2015). "Other variables that have been described as predictors of SBP include C-reactive protein, erythrocyte sedimentation rate, UGIB and hypoalbuminemia." (PMID 24860977, 2014). "Serum laboratory values on admission showed increased inflammation markers C-Reactive Protein (CRP) and procalcitonin, moderately elevated liver enzymes, moderate hypoalbuminemia and severe hyponatremia." (PMID 21235811, 2011). "Laboratory findings showed that non-survivors had significantly higher lactate, CRP, procalcitonin, and liver enzymes and more frequent hypoalbuminemia (84% vs. 53.2%, p < 0.001)." (PMID 40869586, 2025). "CRP, NLR, and hypoalbuminemia are commonly used as potent inflammatory markers." (PMID 40292518, 2025). "Patients with elevated baseline CRP and hypoalbuminemia may benefit from combination therapy (IVIG + GC), while those with high EOS% and low CRP levels could be prioritized for glucocorticoid monotherapy." (PMID 40635748, 2025). "Higher CRP, PCT, BNP and hypoalbuminemia are predictors of MIS-C severity." (PMID 39596959, 2024).
Hypoalbuminemia (continued). "In our study, patient distribution into mGPS and GPS groups was identical as none of the hypoalbuminemia patients (i.e. albumin <35 g/L) had a CRP value <10 mg/L." (PMID 39691271, 2024). "KDSS also has severe manifestations in terms of systemic inflammation (e.g., cytopenia, elevated C-reactive protein [CRP], or hypoalbuminemia) and organ dysfunction (e.g., cardiac, gastrointestinal, or neurologic manifestations); all features are encountered in MIS-C." (PMID 37761488, 2023). "Several hematological markers were reported to suggest a poor prognosis for lung cancer after bone metastasis including hypoalbuminemia, increased ALP and tumor-markers, and systemic inflammation, as evidenced by hyperleucemia, neutrophilia or high C-reactive protein (CRP) level." (PMID 35719977, 2022). "As a result, we might hypothesize that the CRP/Alb ratio (CAR), which is based on both high blood CRP and hypoalbuminemia, might be a stronger predictor of malignancy." (PMID 35547460, 2022). "Previous studies have examined the influence of malnutrition (i.e. hypoalbuminemia) or inflammation (i.e. C-reactive protein) within nonmetastatic RCC patients, identifying both independent prognostic ability as well as synergism with measured sarcopenia." (PMID 36505878, 2022). "Muscle abnormalities neither associated with mGPS classification (p = 0.331) nor elevated CRP level (CRP ≤ 10 vs. CRP > 10, p = 0.584), but all patients with hypoalbuminemia (<35 g/L) had either sarcopenia or myosteatosis or both (p = 0.018)." (PMID 35566781, 2022). "Similarly, majority had hypoalbuminemia (95.4%), raised lactate dehydrogenase (LDH) (93.6%), C-reactive protein (CRP) (98.8%), D-dimer (98.3%), serum ferritin (92.4%) and interleukin 6 level (95.4%)." (PMID 34548976, 2021). "In these studies, the number of patients with hypoalbuminemia in the absence of an elevated CRP concentration who changed from GPS 1 to mGPS 0 was different, with the former being 16/109 (14.7%) and the latter being 52/92 (56.5%)." (PMID 34585050, 2021). "To date, several systemic inflammatory factors, including C-reactive protein (CRP), hypoalbuminaemia, neutrophil-to-lymphocyte ratio (NLR), platelet count, and advanced lung cancer inflammation index (ALI), have been demonstrated to have a prognostic value in LC." (PMID 33916252, 2021). "Additional studies have shown that hypoalbuminemia may even be a valuable tool in monitoring the progression and severity of ARDS, superior to CRP or LDH levels." (PMID 34367693, 2021). "While our study found hypoalbuminemia to be a negative prognostic indicator on its own, previous studies, including that of McMillan and colleagues, found only elevated CRP levels, not hypoalbuminemia, to be negative predictors of survival." (PMID 33446148, 2021). "In our study, BTM ratio was indicative of bone resorption in more than 60% of the patients with cachexia and the main determinants of the negative bone turnover balance were hypoalbuminemia and high CRP." (PMID 34182958, 2021). "CTX is substantially higher in cachectic patients compared to non-cachectic oncological patients and hypoalbuminemia as well as elevated CRP concentrations are independent predictors of a negative bone remodeling balance in cancer patients." (PMID 34182958, 2021). "Irrespective of sex, patients who died during the hospitalization versus those who survived were more likely to have thrombocytopenia, hypoalbuminemia, elevated aspartate aminotransferase (AST) level, elevated C-reactive protein (CRP) level, and elevated creatinine level on admission." (PMID 36168478, 2021). "In summary, this data suggests that among the BIA, anthropometric and laboratory parameters, only hypoalbuminemia and high CRP were predictors of the negative bone remodeling balance of cancer patients." (PMID 34182958, 2021).
Hypoalbuminemia (continued). "However, after pre- and postsurgical albumin infusion or administration of a normal protein diet, the levels of TNF-α, IL-1, IL-6, CRP, and MMP-8 were significantly reduced relative to the hypoalbuminemia group." (PMID 32518615, 2020). "In a group of patients with a severe clinical course, factors such as young age at the time of diagnosis, high erythrocyte sedimentation rates and CRP, high disease activity (Disease Activity Index for Intestinal BD [DAIBD]), and hypoalbuminemia were extracted." (PMID 32377946, 2020). "For the modified GPS (mGPS), patients with hypoalbuminemia were assigned a score of 0 in the absence of an elevated C-reactive protein." (PMID 31998420, 2020). "Patients with elevated CRP (> 1.0 mg/dL) were assigned an mGPS of 1 or 2 depending on the absence or presence of hypoalbuminemia (< 35 g/L), whereas patients with no CRP elevation (≤ 1.0 mg/dL) were assigned an mGPS of 0, even if hypoalbuminemia was present." (PMID 32716955, 2020). "The GPS was calculated as follows: patients with elevated serum C-reactive protein levels and hypoalbuminemia were allocated a score of 2, and those with 1 or no abnormal value were allocated a score of 1 and 0, respectively." (PMID 30535923, 2019). "Our results suggested that hypoalbuminemia, elevated ESR, or increased CRP might be the indications of CE for CAP patients suffered from CD." (PMID 29465542, 2018). "GPS is derived by allocating one point each for elevated CRP (>10 mg/L) and hypoalbuminemia (<3.5 mg/L), so that patients with both, one, or none of these conditions would have scores of 2, 1, or 0, respectively." (PMID 29899304, 2018). "The CKD patients had significantly lower values of Hb, hyperuricemia, and hypoalbuminemia, and higher levels of CRP and LDH than the non-CKD patients." (PMID 29480866, 2018). "The interaction of preoperative elevated CRP and preoperative hypoalbuminemia was not statistically significant, indicating that these two effects do not interfere with each other." (PMID 28740506, 2017). "In the univariate analysis increased age, overhydration, low diastolic blood pressure, the cardiac biomarkers cTNT and NTproBNP, hypoalbuminemia (<36g/l), heart failure but not CRP were predictive of mortality." (PMID 27415758, 2016). "In the univariate analysis, increased age, overhydration, low diastolic blood pressure, raised troponin and NTproBNP, hypoalbuminemia, heart failure but not CRP were predictive of mortality." (PMID 27415758, 2016). "However, the following isolated clinical and laboratory features were deemed not useful in determining taper, including weight change, rash, fatigue, anorexia, fever, white blood count, hypoalbuminemia, hemoglobin level, platelet count, ESR or CRP." (PMID 22931206, 2012). "It was of interest that, in the present study, only seven (14%) patients had hypoalbuminaemia in the absence of an elevated C-reactive protein concentration." (PMID 16479253, 2006). "Also, patients who had a serum CRP level above 10 mg/dL and ALB below 3.5 mg/dL, corresponding to an increased inflammatory status and a progressive nutritional decline, were included in the hypoalbuminemia." (PMID 39000088, 2024). "Therefore, the GPS was modified such that patients with hypoalbuminemia were assigned a score of 0 in the absence of an elevated CRP level." (PMID 39061188, 2024). "In addition to the common inflammatory cytokines such as interleukin (IL)-6, IL-1β, IL-18, tumor necrosis factor (TNFα), IL-8, and C-reactive protein (CRP), hypoalbuminemia and elevated ferritin levels are also considered as inflammatory markers in patients with ESRD." (PMID 37038353, 2023). "Therefore, though hypoalbuminemia is more likely to occur secondary to elevated CRP levels, a crucial difference between the GPS and mGPS or HS-GPS is the inclusion of patients with hypoalbuminemia in the absence of elevated CRP levels." (PMID 34980009, 2022).
Hypoalbuminemia (continued). "Some parameters for which an unfavorable course of the disease has been described are absolute neutrophilia, thrombocytopenia, hypoalbuminemia, the elevation of liver enzymes, creatinine and nonspecific inflammatory markers such as C-reactive protein (CRP) and Interleukin 6 (IL-6)." (PMID 33776561, 2021). "In addition, we identified hypoalbuminemia and high CRP as predictors of the negative bone turnover balance of cancer patients." (PMID 34182958, 2021). "However, the mortality of those with a low albumin and normal CRP level did not increase, which indicated the increased mortality of hypoalbuminemia was partly attributed to inflammation." (PMID 32059708, 2020). "Nonetheless, this dose may not have been enough for other two children, who did not improve their hypozincemia, hypoalbuminemia and high CRP, at the end of the study." (PMID 31694220, 2019). "However, for the modified GPS (mGPS), patients with hypoalbuminemia were assigned a score of 0 in the absence of an elevated C-reactive protein." (PMID 29899304, 2018). "However, infusion of albumin in patients with hypoalbuminemia did not have an effect on the level of CRP." (PMID 24049653, 2012). "However, ROC analysis revealed that GPS had the higher value than hypoalbuminemia or increased CRP alone (data not shown), which may indicate a reciprocal interaction between these two factors." (PMID 30367618, 2018). "We also categorized patients based on cut-off values for high C-reactive protein (CRP) (>0.5 mg/dL) and hypoalbuminemia (<3.8 g/dL) as mGPS of 2 (elevated CRP and hypoalbuminemia), 1 (either elevated CRP or hypoalbuminemia), or 0 (neither elevated CRP nor hypoalbuminemia)." (PMID 26496280, 2015). "Laboratory findings showed severe hypoalbuminemia and elevated levels of ALP and CRP, but all specific autoantibodies examined were negative." (PMID 38540266, 2024). "Baseline and mean CRP had a trend towards negative correlation with LTI; persistent hypoalbuminemia (beta = 0.21, p = 0.01), which was common in chronic inflammation, significantly predicted the decline in LTI." (PMID 36235728, 2022). "There were significant differences between septic patients with and without hypoalbuminemia with regard to the APACHE II score, CRP, blood lactate, WBC count, PT, PCT, MODS incidence, vasopressor administration, ICU stay, and duration of MV." (PMID 26557421, 2015). "High C-reactive protein (range: 29–207 mg/l), an ESR >40 mm/h, hypoalbuminaemia and negative blood cultures were observed consistently." (PMID 21212024, 2011). "Thus, elevated CRP, LDH, and hypoalbuminemia levels are categorized as abnormal because they do not directly threaten patient life." (PMID 30658673, 2019).
Thrombocytopenia (697 papers, 2003 to 2026). A reduction in the number of circulating thrombocytes. "They exhibited the usual biological perturbations associated with leptospirosis, such as high CRP levels, neutrophilia, thrombocytopenia and elevated biochemical markers suggestive of liver and kidney dysfunction." (PMID 40986630, 2025). "Rickettsiosis was associated with a rash (9.06; 3.91–24.9), CRP ≥5 mg/dL (4.03; 1.86–9.81), headache (3.01; 1.75–5.30), thrombocytopenia (2.61; 1.23–6.06), leukopenia (1.88; 1.19–2.98), and temperature ≥39.0 °C (1.66; 1.03–2.68)." (PMID 40094918, 2025). "Other clinical parameters associated with disease severity include CRP and thrombocytopenia, both of which correlated significantly with the measured LDG frequencies." (PMID 39011044, 2024). "Oxygen therapy duration, birth weight < 1500 g, gestational hypertension and CRP levels emerged as independent risk factors for thrombocytopenia in NRDS." (PMID 39380088, 2024). "The incidence of thrombocytopenia and severity of thrombocytopenia were also associated significantly with increased CRP, SAA, and D-Dimer with p values consistently at < 0.005." (PMID 35626194, 2022). "Low platelet-to-lymphocyte ratios, thrombocytopenia, and low lymphocyte-to-C-reactive protein ratios have all been linked to severe disease in new findings." (PMID 36589200, 2022). "In some studies, high-C-reactive protein, eosinopenia, and thrombocytopenia are associated with poor outcomes in AECOPD." (PMID 33957906, 2021). "While limited by sample size and the overall low prevalence of bacteremia, the presence of bandemia, thrombocytopenia, and abnormal CRP were associated with increased likelihood of correct positive prediction." (PMID 32616046, 2020). "The presence of bandemia, thrombocytopenia, and abnormal CRP were associated with increased likelihood of correct positive prediction." (PMID 32616046, 2020). "Leukopenia (white blood cell count < 4000/mm3; odds ratio [OR] 30.13), thrombocytopenia (platelet count < 80,000 /mm3; OR 19.73) and low C-reactive protein (< 1 mg/dL; OR 67.46) were consistent risk factors for SFTS (all P < 0.001)." (PMID 30782137, 2019). "The biological profile of NE is characterized by acute kidney injury (AKI) associated with proteinuria, thrombocytopenia, and biological inflammatory syndrome, including elevated leukocyte count and C-reactive protein level." (PMID 29774835, 2018). "A significant increase in the SOFA scores (p < 0.001), incidence of acidosis, episodes of hypotension, thrombocytopenia, and CRP concentrations were associated with decreases in the serum albumin levels." (PMID 30423847, 2018). "We found leukopenia, thrombocytopenia, and high CRP levels to be associated with mortality in pediatric IPD, and these factors are worthy of special attention at admission." (PMID 28149700, 2017). "HGA is an acute febrile illness that causes headache, myalgia, malaise, elevated levels of C-reactive protein and serum transaminases, leukopenia, and thrombocytopenia; the disease seems to have milder manifestations in Europe than in the United States." (PMID 22841007, 2012). "Logistic regression analyses were then carried out to evaluate the associations of high CRP and high IL-6 with high serum creatinine, thrombocytopenia, or hospitalization exceeding seven days." (PMID 20500875, 2010). "High IL-6 was found to be an independent risk factor for impaired renal function, thrombocytopenia, and longer hospitalization, when examined together with high CRP and age." (PMID 20500875, 2010). "Our analysis showed that thrombocytopenia was independently associated with in-hospital mortality, even after adjusting for known predictors such as age, gas exchange, CT severity score, creatinine, and CRP." (PMID 41140677, 2025). "Similarly, high CRP levels, leukopenia and thrombocytopenia are associated with mortality in paediatric patients with IPD, and these factors warrant special attention upon admission." (PMID 38898407, 2024).